FASLG (Fas ligand)
Diseases named in the same sentence as FASLG in open-access papers (continued):
Sharing a sentence is not in itself a finding about the gene and the disease.
tumor (continued). "M1 also play an important role in tumor suppression through the generation of cytotoxic molecules such as TNF-α-related apoptosis inducing ligand (TRAIL) or FAS ligand (FASL), or via the Antibody-Dependent Cellular Phagocytosis (ADCP) or Antibody-Dependent Cell-mediated Cytotoxicity (ADCC)." (PMID 36325334, 2022). "Furthermore, the enrichment of IL-10, VEGF and prostaglandin E2 under hypoxic conditions induces Fas-ligand expression on the tumour vasculature to promote T-cells apoptosis, ultimately leading to reduced T-cell accumulation within the TME." (PMID 33923305, 2021). "Tumor vascular ECs can reduce the recruitment and activation of cytotoxic T lymphocytes (CTLs) by expressing a variety of immunosuppressive molecules, such as programmed cell death 1 ligand 1/2 (PD-L1/2), Fas ligand (FasL)." (PMID 34930293, 2021). "However, the TIGIT-related communication was a little stronger within hypoxia T cells, while tumor necrosis factor (TNF)- and FASLG-related communications were stronger in normoxia between T cells and tumor cells." (PMID 34956900, 2021). "Finally, T cells traffic to the tumor bed and infiltrate the tumor tissue, where activated T cells kill cancer cells via Fas–Fas ligand interaction or by secreting cytotoxic granules containing granzyme and perforin." (PMID 33466674, 2021). "Exosomes isolated from tumor cell supernatants or cancer patients show a rich expression of Fas ligand (FasL), PD-L1, IL-10, TGF-β, tumor-associated antigens, and ectoenzymes engaged in the adenosine pathway (CD39 and CD73), which all contribute to immunoevasion." (PMID 34948368, 2021). "Antigen-specific CD8+T cells may infiltrate the tumor and represent the major effector T lymphocytes able to kill cancer cells by granule exocytosis, Fas ligand (FasL)-mediated apoptosis and by secreting interferon (IFN)-γ and tumor necrosis factor (TNF)-α." (PMID 33920505, 2021). "The cytotoxic effects of NKEVs were shown to be partly abolished by antibodies against Fas or Fas ligand (FasL), suggesting that ligand–receptor interaction is another mechanism by which NKEVs are targeted to tumor cells, although this has yet to be demonstrated experimentally." (PMID 34093547, 2021). "Fas ligand has been demonstrated to be functionally competent on tumor endothelium." (PMID 35096619, 2021). "Furthermore, tumour necrosis factor-related apoptosis inducing ligand (TRAIL) and Fas ligand (FasL) can be expressed on tumour ECs, selectively killing effector T cells." (PMID 33917287, 2021). "Another mechanism that prevents T cell infiltration into the tumors relies on the overexpression of Fas ligand (FasL) on TEC surface that causes the selective killing of tumor-specific CD8+ T cells and to the accumulation of FoxP3+ T regulatory (Tregs) cells within the tumors." (PMID 33554861, 2021). "Tumor-associated astrocytes mediate the transcriptional reprogramming in myeloid cells toward an anti-inflammatory phenotype and can directly inhibit the cytolytic lymphocytes by expressing PD-L1 and/or Fas ligand (FasL), thereby repressing anti-tumor immune functions." (PMID 33804873, 2021). "Furthermore, FASLG was negatively correlated to Ki-67 and was more frequently expressed in well-differentiated tumours." (PMID 32606315, 2020). "A correlation between FASLG and differentiation was seen in the immunohistochemical results where well-differentiated tumours were significantly more immunoreactive for FASLG compared to poorly differentiated tumours." (PMID 32606315, 2020). "Besides, tumor-derived Fas ligand promotes apoptosis of activated T cells and leads to an immune escape of tumor cells by inhibiting dendritic cells and maturation of T cells." (PMID 33329549, 2020). "In addition, NK cells induce the expression of FasL/Fas (FAS/FASLG), leading to apoptosis of tumor cells, and also affect tumor cells via multiple approaches, including direct lysis by perforin 1 (PRF1) and granzyme A and B (GZMA and GZMB)." (PMID 33276627, 2020).
tumor (continued). "Activated NK cells induce the activation of a caspase cascade and ultimately, apoptosis occurs in tumor cells via the stimulation of Fas receptor on tumor cells interacted with Fas ligand on NK cells and the release of granules, such as granzymes and perforin from NK cell into the tumor cells." (PMID 32397120, 2020). "Also, patients with well-differentiated tumours had a significantly higher expression of FASLG compared to patients with poorly differentiated tumours, 100% vs. 30% of tumours being positive." (PMID 32606315, 2020). "The correlation of FASLG to Ki-67 and differentiation may be indicative of a possible new mechanism for FASLG in PanNENs G3 through an anti-tumour effect, although further studies are needed to confirm these findings." (PMID 32606315, 2020). "Additionally, PD-L1 expression on tumor cells regulates several cell-intrinsic mechanisms promoting tumor cell growth, metastasis, and resistance to Fas-ligand as well as chemotherapy-induced apoptosis." (PMID 32486375, 2020). "The clinical relevance of FASLG protein expression in tumour cells is not fully understood." (PMID 32606315, 2020). "Seven out of 14 (50%) specimens were immunoreactive for FASLG in the tumour cells." (PMID 32606315, 2020). "Nevertheless, too little has been studied on the differences between soluble (i.e. sera concentrations of FASLG) and tissue expressed FASLG and which of the two that may be the driving factor for tumour progression." (PMID 32606315, 2020). "Many tumor-derived EVs are rich in the pro-apoptotic Fas ligand (Fas-L)." (PMID 32150875, 2020). "Studies have shown that activated T-cells can be de-activated by FASLG expressed on tumour cells." (PMID 32606315, 2020). "The abnormal FAS/FAS ligand (FASL) pathway is not only related to tumorigenesis and development but also may be related to the sensitivity of tumor cells to some chemotherapy drugs." (PMID 33150184, 2020). "Moreover, the tumor endothelium can release FASLG, leading to apoptosis of T cells when they are trying to transmigrate the tumor vessel." (PMID 33381115, 2020). "So too, EVs carrying death-inducing cytotoxic cytokines TNF, TNF-related apoptosis-inducing ligand, TRAIL, and Fas ligand (FasL) induces apoptosis of tumor-specific T cells, and exosomal EVs block NKG2D to inhibit NK cell activation and NK tumoricidal activity." (PMID 30895170, 2019). "Tumor cells could be depleted by tumor infiltrating lymphocytes through Fas ligand-mediated apoptosis." (PMID 31552181, 2019). "Indeed, several tumor-derived EVs have been shown to be enriched for Fas ligand (Fas-L) which induces cell apoptosis when binding to its receptor." (PMID 30925923, 2019). "However, they can recognize the tumor-antigen-MHC-I-complex in the presence of antigen presenting cells (APCs), and thereby destroy tumor cells through the perforin-granzyme B- and/or Fas-Fas ligand axis-mediated apoptosis." (PMID 30823602, 2019). "This extends to MHC class II induction on M1 macrophages, which can trigger IFN-γ release by Th1 cells to further activate macrophages that express abundant antitumor cytokines and factors, such as fas ligand (FASL) and nitric oxide (NO), and directly phagocytose tumor cells." (PMID 31842362, 2019). "Furthermore, autophagy plays a role in the response of death receptor agonists to block tumor cell proliferation, Fas ligand (FasL), and tumor necrosis-like apoptosis-inducing ligand (TRAIL)." (PMID 30678689, 2019). "Fas-Ligand activates Fas receptors in tumor cells which induces their apoptosis." (PMID 31157216, 2019). "In vitro blocking experiments showed that granzyme B inhibitor efficiently suppressed the cytotoxicity of CD8+NKT-like cells against tumor cells and MDSCs, while Fas ligand (FasL) or tumor necrosis factor-related apoptosis-inducing ligand (TRAIL) inhibition failed to produce similar effects." (PMID 31278476, 2019).
tumor (continued). "Also correlating were GZMB and FASLG, both necessary for anti-tumor CD8 T cell cytotoxic functionality, PD-1 and LAG3, representing T cell activation and exhaustion, and TAP2, necessary in MHC I antigen presentation." (PMID 29487705, 2018). "Importantly, the tumor cytotoxic molecules, including perforin, granzyme, and Fas ligand, were characteristically expressed in the late stages of CIK differentiation." (PMID 30333226, 2018). "Apoptosis of tumor-infiltrating lymphocytes can be prevented by interrupting the Fas/Fas-ligand axis, and is triggered by polymorphonuclear-myeloid-derived suppressor cells, which express high levels of Fas-ligand and are enriched in TiRP tumors." (PMID 29123081, 2017). "The observed clustering of mIFN-DCs and tumour cells might facilitate tumour killing via either cell surface TRAIL or Fas ligand." (PMID 28191816, 2017). "Moreover, Sias have also been described to take part in the hypersialylation process of Fas receptor (CD95) on tumor cells, damping its binding to the Fas-ligand (CD95L) expressed by CTLs." (PMID 27014629, 2016). "Moreover, the EV-mediated transfer of Fas ligand from tumor cells to activated T cells has been shown to induce T-cell apoptosis leading to tumor immune escape." (PMID 26334526, 2015). "Also, Fas ligand can be transferred from tumor cells by extracellular vesicles provoking activated T cell apoptosis." (PMID 23908664, 2013). "Tumor cells and other cells in the tumor microenvironment secrete cytokines such as IL-6, indolamine-2,3-dioxygenase, vascular endothelial growth factor, programmed death-1 ligand, and soluble Fas ligand, which hamper antitumor immunity and promote tumor growth." (PMID 24213505, 2012). "Finally, CD8+ T cells from cancer patients have been shown to undergo apoptosis in response to tumor-derived microvesicles expressing tumor antigens, Fas ligand and MHC class I." (PMID 22369276, 2012). "The binding of the Fas ligand (FasL) on the tumor cell to the Fas receptor on the T-cell, a hypothesis known as tumor counterattack, has been suggested as responsible for T-cell death." (PMID 23118782, 2012). "For example, MMP7 could cleave Fas ligand, thereby lowering the impact of chemotherapy on the tumor by abrogating apoptosis." (PMID 21857934, 2011). "Fas ligand is a potent pro-apoptotic molecule expressed by cytotoxic effector T and NK cells that is known for its ability to eliminate virally infected target populations, tumor cells, and autoreactive T and B cells." (PMID 21479271, 2011). "Tumor cells have evolved multiple tactics to evade the immune system: they can express immunosuppressive cytokines, down-regulate Major Histocompatibility Class I molecules, and even express Fas ligand to kill reactive cytotoxic lymphocytes." (PMID 21994711, 2010). "Other causes include secretion of inhibitory substances e.g. IL-10, TGF-β, abnormal T-lymphocyte signal transduction and expression of Fas ligand, which may enable tumour cells to induce apoptosis in Fas expressing tumour infiltrating lymphocytes." (PMID 20181099, 2010). "Upregulation of Fas ligand (FasL/CD95L) expression by tumour cells may represent one such mechanism." (PMID 18648368, 2008). "Fas ligand (FasL) is expressed on some cancers and may play a role in the immune evasion of the tumour." (PMID 11104571, 2000). "Additionally, ICOS ligand and FASLG could suppress tumor growth and extend survival in patients with NSCLC." (PMID 40747615, 2025). "NKs attack tumor cells directly by mechanisms such as release of lytic granules/granzymes and triggering receptor-mediated cell death via overexpression of death ligands like Fas ligand (FasL) or tumor necrosis factor (TNF)-related apoptosis-inducing ligand (TRAIL)." (PMID 40007761, 2024).
tumor (continued). "Tumor cells may evade destruction by the immune system through the expression of Fas ligand." (PMID 39917362, 2024). "Thus, tumor cells can use FASLG to suppress the attack by the immune system." (PMID 39068622, 2024). "In addition, N1 TANs may also suppress tumour cell proliferation via Fas/FasL (Fas ligand) pathway, activation of caspase cascade mediated cell cycle arrest and apoptosis of cancer cells." (PMID 36980527, 2023). "High levels of expression of GZMB and FASL (encoding Granzyme B and Fas ligand) but low levels of IFNG and TNF (encoding Interferon-γ and TNF-α) in these exhausted-like T cells are suggestive of an altered cytotoxic profile but remaining capacity for tumor cell killing." (PMID 36609566, 2023). "Interestingly, a proteomic analysis of tumor-derived exosomes (TEXs) cargo revealed that they contain MHC molecules as well as the pro-apoptotic member of the TNF family—Fas ligand (FasL), which induces apoptosis of T cells and thus has anti-inflammatory effects." (PMID 37761972, 2023). "In addition, ECs in lung cancer express high levels of Fas ligand to trigger the apoptotic pathway in tumor-infiltrating cytotoxic T cells, but also the inhibitory molecule PD-L1 to suppress the activation of effector T cells, indicating their immunosuppressive roles." (PMID 36901858, 2023). "The FASLG gene and FasL protein are overexpressed in many cancers, either by cancer cells themselves or by cells constituting the TME, such as regulatory T cells (Tregs), myeloid-derived suppressor cells (MDSCs), cancer-associated fibroblasts (CAFs), and tumor endothelial cells." (PMID 37200859, 2023). "However, it was reported that the expression of FASLG by apoptosis-resistant tumor cells could fight against antitumor cells." (PMID 35387121, 2022). "Moreover, MPs may trigger T cell-activated apoptosis by exposing the Fas ligand, which might contribute to immune suppression and indirectly promote tumour growth." (PMID 36064415, 2022). "In addition to CAF-derived soluble factors CXCL12, IL-6, and TGF-β, CAFs also inhibit antitumor cytotoxicity of CD8+ T cells through the acquisition of immune checkpoint molecules, such as programmed cell death ligand 1 (PD-L1), PD-L2, and Fas ligand in several tumor types." (PMID 33673405, 2021). "In addition, oe-CASC7 lowered the expression of ki67 while elevated the FASLG level in the tumor." (PMID 34889164, 2021). "Interestingly, recent studies have shown that CAFs isolated from murine lung adenocarcinomas and melanoma tumours can directly induce apoptosis in tumour-specific CD8+ T cells through simultaneous upregulation of PD-L2 and Fas ligand, leading to increased tumour survival." (PMID 32967079, 2020). "Therefore, tumor-infiltrating lymphocytes apoptosis is a relevant mechanism of immunotherapy resistance, which could be blocked by interfering with the Fas/Fas-ligand pathway." (PMID 29123081, 2017). "This may be an effect of overall tumor burden possibly due to an immunosuppressive function of the tumors, e.g. due to the production of immunosuppressive cytokines like TGFβ and IL-10 or the expression of Fas ligand on the tumor cell surface." (PMID 25121970, 2014). "FASLG may regulate immune evasion of tumour cells by inducing apoptosis in cytotoxic T lymphocytes." (PMID 22894607, 2012). "In addition, activated T cells may exert direct activity on tumor cells through apoptotic pathways such as the engagement of Fas ligand, which is highly expressed on activated T cells, and Fas receptor on tumor cells." (PMID 20178622, 2010). "In addition, Fas ligand-positive tumours may evade immune surveillance by killing Fas-positive tumour-infiltrating cells." (PMID 19114018, 2008). "The crosstalk interaction between tumour cells and adjacent stromal cells participates in tumour immune escape, spreading and angiogenesis, which is conducted by a number of soluble and membrane molecules, including soluble Fas, Fas ligand, soluble MMPs, soluble VEGF and EMMPRIN." (PMID 17088917, 2006).
tumor (continued). "T cells and their effector functions, in particular the canonical cytotoxicity of CD8+ T cells involving perforin, granzymes, Fas ligand (FasL), and tumor necrosis factor related apoptosis inducing ligand (TRAIL), are crucial for tumor immunity." (PMID 40397730, 2025). "Previous studies have suggested that the clearance of tumor cells is accomplished by activated CD8+ T cells through the utilization of the perforin-granzyme- and Fas-L/Fas ligand pathways." (PMID 40140647, 2025). "CAR-NK cells are cytotoxic innate lymphoid cells that eliminate tumor cells through the release of granzyme B, perforin, TRAIL, and Fas ligand." (PMID 40723278, 2025). "Bregs express inhibitory molecules such as Fas Ligand (FasL) and PDL-1 and can support tumor progression by suppressing anti-tumor immune responses." (PMID 39940924, 2025). "NK cells also express members of the TNF family proteins such as Fas ligand (FasL) or TNF-related apoptosis-inducing ligand (TRAIL), which induce tumor cell death by interacting with their respective receptors." (PMID 40519272, 2025). "FAS ligand (FASL/CD95L), a regulator of T-cell homeostasis through apoptosis, is also expressed on tumour vasculature in humans and mice." (PMID 40361472, 2025). "Concurrently, IFN-α upregulates Fas ligand (FasL) and TNF-α, which engage corresponding death receptors on tumor cells to trigger the extrinsic apoptotic pathway." (PMID 41359111, 2025). "Another important mechanism is Fas-Fas Ligand (FasL) mediated apoptosis, in which CAR-T cells express FasL, which binds to Fas (CD95) receptors on tumor cells, activating the caspase cascade, ultimately leading to programmed cell death." (PMID 40312353, 2025). "Further, curcumin downregulated the gene expression of factors secreted by tumor cells known to induce immunosuppression (VEGFA, PDGF, IL4, OSM, CXCR4 and Fas ligand)." (PMID 39861845, 2024). "EVs carrying TNF, Fas ligand (FasL) and tumor necrosis factor-related apoptosis-inducing ligand (TRAIL) on their surfaces are able to induce apoptosis in tumor cells if the receptors for these ligands are present on their surfaces." (PMID 38474125, 2024). "Tumor-derived VEGFA, IL-10 and prostaglandin E2 cooperatively induce upregulation of the death mediator Fas ligand (FasL) in ECs which gain the ability to kill effector CD8+ T cells but not Treg cells (due to expression of FoxP3)." (PMID 38426109, 2024). "Various death ligands, such as tumour necrosis factor (TNF)-α, Fas ligand, and TNF-related apoptosis-inducing ligand (TRAIL), are expressed on the membrane of CD8+ T cells or secreted from these cells and induce tumour cell apoptosis." (PMID 38893071, 2024). "On the other hand, Fas ligand (FasL) is expressed on NBL cells and neutralizes infiltrated T cells, which not only makes the TME more permissive to native tumor growth, but also adds complexity to the design and development of potential immunotherapies." (PMID 39199637, 2024). "The list of genes that occur more frequently in the liver of these two strains also includes FASLG and TNFSF8, which belong to the tumour family of tumour necrosis factor." (PMID 39342330, 2024). "Direct release of perforin and granzymes, as well as the induction of apoptosis through ADCC effects, Fas ligand (FasL), or TNF-related apoptosis-inducing ligand (TRAIL), represents the tumor-killing toolkit of activated NK cells." (PMID 38404574, 2024). "By immune phenotyping, we observed an upregulation in the expression of T cell-suppressive molecules, PD-L1, Fas Ligand (FasL), and ARG1 across moDC, M-MDSC, and G-MDSC subsets from day 5 to day 11 post-tumor induction." (PMID 38577107, 2024). "Low-dose external radiation has demonstrated to sensitize tumor cells to T cell cytolytic activity through mechanisms involving tumor necrosis factor-related apoptosis-inducing ligand (TRAIL) and Fas ligand (FasL)." (PMID 38550578, 2024).